LRRIQ3 (leucine rich repeats and IQ motif containing 3)
Synonyms: LRRC44; MGC22773
Tractability: Antibody: the Human Protein Atlas places it where antibodies can reach.
Gene: Protein-coding gene on chromosome 1 (74,026,015 to 74,198,187, reverse strand). Ensembl gene ENSG00000162620.
Subcellular location (Human Protein Atlas): Plasma membrane; Nucleoplasm
Gene Ontology:
Molecular function: protein binding
Genetic constraint (gnomAD): Loss-of-function variants: 49 observed, 38.78 expected, observed/expected ratio (o/e) 1.26, 90% interval 1 to 1.6. The upper end of that interval is the gene's LOEUF score, 1.6, which puts it in group 6 of 6, group 1 being the genes least tolerant of losing a copy. Missense variants: 579 observed, 504.99 expected, observed/expected ratio (o/e) 1.15, 90% interval 1.07 to 1.23. Synonymous variants: 182 observed, 168.41 expected, observed/expected ratio (o/e) 1.08, 90% interval 0.96 to 1.22.
Homologues: Orthologues: chimpanzee LRRIQ3 (98% identical), macaque LRRIQ3 (93% identical), dog LRRIQ3 (73% identical), pig LRRIQ3 (72% identical), rabbit LRRIQ3 (71% identical), mouse Lrriq3 (62% identical), rat Lrriq3 (62% identical), tropical clawed frog lrriq3 (29% identical), zebrafish lrriq3 (17% identical), Drosophila melanogaster TbCMF46 (8% identical), Drosophila melanogaster Ppr-Y (8% identical). Paralogues in human: LRRC9 (14% identical), CEP97 (13% identical), LRRCC1 (13% identical), LRGUK (12% identical), LRRC49 (10% identical), LRRC43 (10% identical), DRC3 (10% identical), DNAAF1 (9% identical), DNAAF11 (9% identical), LRRC46 (8% identical), LRRC23 (7% identical), PPP1R42 (6% identical), and 1 more.
Diseases named in the same sentence as LRRIQ3 in open-access papers:
LRRIQ3 is named in the same sentence as 5 diseases in open-access papers, as found by Europe PMC text mining. Sharing a sentence is not in itself a finding about the gene and the disease. The quoted sentences say what the papers report.
Hypertension (1 paper, 2012). The presence of chronic increased pressure in the systemic arterial system. "The rs1384883 SNP from LRRIQ3 was reported in a GWAS of blood pressure and hypertension, while other SNPs associated with the ASE of the LRRIQ3 transcript were reported in gene expression studies." (PMID 22685595, 2012).
neurodevelopmental disorder (1 paper, 2021). A behavioral and cognitive disorder with onset during the developmental period that involves impaired or aberrant development of intellectual, motor, or social functions. "LRRIQ3 is linked with neurodevelopmental disorders and delayed puberty." (PMID 34198905, 2021).
LRRIQ3 also shares sentences with these, for which no sentence is quoted: major depressive disorder (1 paper); rectal cancer (1); tumor (1).